CTLA4 (cytotoxic T-lymphocyte associated protein 4)
Diseases named in the same sentence as CTLA4 in open-access papers (continued):
Sharing a sentence is not in itself a finding about the gene and the disease.
Immunodeficiency (continued). "Comparing and contrasting these phenocopies with IEIs of CTLA4 and PDCD1 might advance our understanding of the actions of CTLA4 and PD-1, and how defective expression of these molecules cause immune deficiency and dysregulation." (PMID 35154081, 2021). "Since no diagnostic details are given, the exclusion of combined immune deficiencies involving T-cell immunity as well as B-cell failure, or known mutations in monogenic disease (e.g. CTLA4, LRBA, KMT2D, XIAP, RAG1, NFKB1) is unclear." (PMID 33329602, 2020). "Furthermore, we did not observe any substantial differences considering PMN and monocyte immunophenotyping between CTLA4-mediated immunodeficiency and the rest of the PAD patients, in all experimental conditions analyzed." (PMID 33274244, 2020). "Similarly, other immune disorders and cancers may be treated with monoclonal antibodies targeting cancer-specific antigens or immunosuppressive molecules present on immune cells such as cytotoxic T-lymphocyte-associated protein 4 (CTLA-4) and programmed cell death-1 (PD-1)." (PMID 32259744, 2020). "Inhibitory pathways including the programmed cell death-1 (PD-1)/programmed death ligand-1 (PD-L1) interaction, cytotoxic T-lymphocyte-associated antigen 4 (CTLA-4) and killer cell immunoglobulin-like receptors (KIR) have also been shown to play important roles in MM immune dysfunction." (PMID 32138182, 2020). "So these variations may influence biological function of CTLA-4/IL-18, result in immune dysfunction, impact anti-viral immune responses and ultimately confer susceptibility to viral hepatitis." (PMID 31801640, 2019). "CTLA4, a negative regulator in auto-immune diseases, participates in the pathways of CAMs and T cell receptor signalling contributing to autoimmune tissue destruction and it might exert a down-regulatory effect on TNF-α, TGF-β, IL1-β and IL16 production." (PMID 29401671, 2018). "Individually targeting CD28, CTLA-4 and PD-L1 might therefore represent a valuable therapeutic strategy to treat immune disorders where effector and regulatory T cell functions need to be differentially targeted." (PMID 24376655, 2013). "The immune dysfunction of aTreg was accompanied by the abnormal expression of CTLA-4." (PMID 23776439, 2013). "Finally, certain manifestations of primary CTLA4 deficiency are not seen in the drug-induced setting, significantly immunodeficiency, which is contributed to by autoantibody mediated cytopenia, lymphadenopathy and splenomegaly." (PMID 35912205, 2022). "We, therefore, suggest that the combination of the loss-of-function mutation in CTLA-4 with the gain-of-function mutation in JAK3 directs the differentiation of CD4 T cells into dysfunctional TFH cells supporting the development of lymphadenopathy, hypogammaglobulinemia, and immunodeficiency." (PMID 29375547, 2017). "Thus, individually targeting CD28, CTLA-4 and PD-L1 with biological agents might represent a valuable therapeutic strategy to treat immune disorders where Teff and Treg functions need to be differentially targeted." (PMID 24376655, 2013). "PD-1, CTLA4, LAG3, and HAVCR2 are T cell depletion markers, and the T cell depletion is a major factor contributing to immune dysfunction in cancer patients." (PMID 36785788, 2023). "It seems that the high expression of the CTLA-4 molecule in both Hodgkin’s lymphoma and CLL significantly influences the biology and mechanisms of cellular immune disorders in these diseases." (PMID 35158937, 2022). "The assessment of antigens related to immune regulation, such as FOXP3 and CTLA4, is also of some help, but NGS panels are increasingly adopted in subjects with immunodeficiency and lymphoproliferation." (PMID 33809703, 2021). "Using heat maps to depict variations from normal in patients with known mutations in TNFRSF13B, CTLA4, and CARD11, we asked whether we could identify trends within defined cellular populations that might be relevant to the genetic pathogenesis of their immunodeficiency." (PMID 31572362, 2019).
Immunodeficiency (continued). "Thus, PD-1/CTLA-4 blockade may be even more effective for controlling EBV-positive lymphomas in the context of certain types of human immunodeficiency (for example, following solid organ transplantation), where EBV-specific memory T cells and/or NK cells are present." (PMID 27186886, 2016). "In contrast, the NC sample (cHC-1L) displayed a more robust immune-infiltrated phenotype, but with signs of immune dysfunction; the expression levels of T-cell exhaustion markers like PDCD1 and CTLA4 were significantly higher than in the CC sample (P < 0.0001)." (PMID 41235234, 2025). "CTLA-4 interacts with CD80, thereby limiting T-cell activation and leading to immune dysfunction." (PMID 38983866, 2024). "Predicting the therapeutic efficacy of ICI (anti‐PD‐1/anti‐CTLA4) may be done using the TIDE score, which measures tumor immune dysfunction and rejection." (PMID 37903487, 2024). "Based on the weighted gene co-expression network analysis (WGCNA), the purple gene module was most negatively correlated with the grouping, TEX, CTLA-4, LAG-3, PD-L1, and immune dysfunction score, while the yellow module was most positively correlated with these markers." (PMID 39872516, 2024). "Therefore, the aim of this publication was to evaluate three immunological checkpoints of their ligands: PD-1 (CD279)/PD-L1 (CD274), CTLA-4 (CD152)/CD86, and CD200R/CD200 in the course of immunodeficiencies, on the example of CLL and CVID." (PMID 37958359, 2023). "However, whether the increase of CD21lo B cells observed in CTLA-4 haploinsufficiency is a direct consequence of the genetic mutation, a result of chronic infection secondary to the immunodeficiency, or a reflection of CTLA-4 pathway disruption, is not clearly understood." (PMID 31156616, 2019). "By contrast, increased CTLA-4 expression on HIV-specific CD4 (but not CD8) T cells is strongly associated with disease progression and reversible immune dysfunction in HIV-infected patients." (PMID 19247441, 2009). "Interestingly, immunodeficiency observed in humans with CTLA4 haploinsufficiency is not observed in Ctla4-/- mice." (PMID 35154081, 2021). "Here, we show that both hyperactivated CTLA-4 and FOXP3 are related to an unfavorable prognosis, and the amount of CTLA-4+ TILs is higher than FOXP3+ Tregs, which indicates that besides FOXP3+ Tregs, other CTLA-4+ TILs may be involved in antitumor immune disorders." (PMID 34526987, 2021). "Importantly, because incomplete T cell differentiation may arise early in the course of tumor progression and is not overcome by CTLA‐4 or PD‐1 blockade, this form of immune dysfunction may indeed contribute to the innate resistance to checkpoint blockade therapy exhibited by many cancers." (PMID 39930625, 2025).
glioblastoma (96 papers, 2012 to 2025). The most malignant astrocytic tumor (WHO grade IV). "Intracerebral administration of nivolumab and ipilimumab (CTLA-4 monoclonal antibody) was well-tolerated and associated with encouraging OS in recurrent glioblastoma patients with maximal safe resection." (PMID 37705736, 2023). "Of these IC, the most studied are IDO, PD-1, and CTLA-4 that are implicated in the progression of glioma and glioblastoma and, for this reason, have been considered as potential targets for immunotherapy." (PMID 35328349, 2022). "The immune checkpoint inhibitor ipilimumab targets cytotoxic T-lymphocyte-associated protein 4 (CTLA-4) and has shown clinical efficacy in preclinical models of glioblastoma." (PMID 32164579, 2020). "PD-L1 (programmed death ligand 1) and CTLA-4 (Cytotoxic T-lymphocyte-associated protein 4) have been identified as alternatives for immunosuppression in glioblastomas." (PMID 28223536, 2017). "Use of multiple combinations of immunotherapies for targeting the over-expressive immunosuppression by PD-L1 (programmed cell death protein - ligand 1) and CTLA4 (cytotoxic T-lymphocyte-associated antigen 4) have effective potential in the suppression of glioblastoma." (PMID 37937301, 2023). "Immune checkpoint inhibitors (ICIs) such as anti-programmed cell death protein-1 (PD-1)/programmed death ligand-1 (PD-L1) and anti-cytotoxic T-lymphocyte-associated protein 4 (CTLA-4) have been extensively studied for both primary and recurrent glioblastomas in medical research." (PMID 33193404, 2020). "Ipi-Glio is the first clinical trial to evaluate the efficacy of the addition of a CTLA-4 inhibitor to standard therapy in glioblastoma." (PMID 40800123, 2025). "Co-expression profiles of PD-1 and CTLA-4 in glioblastoma gave rise to the clinical trials of the corresponding blockers." (PMID 40895574, 2025). "Gene expression analysis of in-house glioblastoma samples confirmed that HAVCR2 expression was higher than other well-known immune checkpoint inhibitors such as CTLA4, PD-1, PD-L1, PD-L2, and IDO1." (PMID 40072074, 2025). "Align with these studies, glioblastoma-derived EVs enriched with immunosuppressive molecules, including FasL, CTLA-4, CD39, and CD73 suppress the expression of NKG2D in NK cells, thereby mitigating NK cell activation." (PMID 40908470, 2025). "Glioblastoma-derived EVs enriched with FasL and CTLA-4 activate the NF-κB pathway in macrophages, which promotes M2 macrophage polarization to reshape an immunosuppressive TME." (PMID 40908470, 2025). "Clinical studies have demonstrated that PD-L1–positive patients benefit significantly from combination therapy with PD-1 inhibitors (such as pembrolizumab) and CTLA4 inhibitors (such as ipilimumab), which markedly improves survival in recurrent glioblastoma." (PMID 40661083, 2025). "In glioblastoma, CTLA-4 competes with CD28 for binding to costimulatory molecules (CD80 and CD86) on APCs, thereby inhibiting the activation of T cells." (PMID 41208963, 2025). "In a study on the mechanism of glioblastoma resistance, the combination of PD-1 and CTLA-4 antibodies was applied to treat glioblastoma mice." (PMID 38787372, 2024). "In glioblastoma model, the combination of CD73 deficiency with RT and anti-CTLA-4 and anti-PD-1 therapies has also exhibited synergistic effects." (PMID 39285178, 2024). "In pediatric tumors, the expression of CTLA-4 was detected in glioblastoma, neuroblastoma, and sarcomas, particularly in osteosarcoma, suggesting its potential role as a target for immunotherapy." (PMID 38542199, 2024). "Evidence has shown that KD can lead to a downregulation of CTLA-4 and PD-1 expression on tumor-infiltrating lymphocytes (TILs), as well as PD-L1 expression on glioblastoma cells in animal models." (PMID 37764768, 2023). "Targeting specific TAM subpopulations, such as CD73+ cells, extended the survival of mice with glioblastoma and showed synergistic effects when combined with anti-PD-1 and anti-CTLA-4 therapy." (PMID 38136335, 2023).
glioblastoma (continued). "Several ongoing clinical trials have provided preliminary evidence that injection of a combination of anti-CTLA4 and anti-PD-1 mAbs directly into sites of glioblastoma resection is safe." (PMID 36768997, 2023). "Anti‐CTLA‐4 antibody alone or in combination with anti‐PD‐1 antibody significantly prolonged the long‐term survival of the immunocompetent murine glioblastoma model." (PMID 35142109, 2022). "Among all markers investigated, the immune checkpoint cytotoxic T lymphocyte-associated protein 4 (CTLA4; CD152) was the only marker found to be increased on circulating monocytes in glioblastoma patients." (PMID 36497232, 2022). "Through a similar mechanism, glioblastoma cells also can upregulate CTLA-4, which promotes T-cell anergy through blockade of the B7/CD28 co-stimulatory signal." (PMID 35406398, 2022). "The absence of CD73 significantly improved survival in a murine model of glioblastoma multiforme treated with anti-CTLA-4 and anti-PD-1, suggestive of CD73 as a combinatorial target in glioblastoma." (PMID 35428347, 2022). "In this context, different antibodies against CTLA-4 and PD-1 have been developed for clinical purposes and used for immunotherapy in pediatric patients with glioblastoma." (PMID 35328349, 2022). "Due to CTLA-4 pathway therapy, there is an increased number of T-regulatory (Treg) cells in glioblastoma multiforme." (PMID 35103180, 2021). "A high rate of infiltrating Treg expressing CTLA-4, with increased suppressive functions, was detected in glioblastoma patients." (PMID 33920505, 2021). "Wainwright and coworkers setup an orthotopic model based on intracranial injection of glioblastoma cell lines and treatment with blocking antibodies against PD-L1 or other immune checkpoints, such as CTLA-4 and IDO." (PMID 33920505, 2021). "Anti-IDO in combination with anti-PD-1 and anti-CTLA-4 approaches are more potent than monotherapy and decrease the accumulation of Tregs in a glioblastoma murine model." (PMID 33572835, 2021). "Similar results were obtained in an orthotopic model of glioblastoma where the highest curative effect was obtained using a combination of anti-CTLA-4 and anti-PD-1 antibodies in addition to oncolytic viruses." (PMID 33920505, 2021). "CTLA-4 expression was detected in different adult cancers and in pediatric solid tumors, such as glioblastoma and NB." (PMID 33920505, 2021). "Similar effects were observed in an orthotopic model of glioblastoma, in which anti-CTLA-4 alone displayed only marginal effects in terms of reduction in tumor growth and prolonged overall survival." (PMID 33920505, 2021). "CTLA-4 showed stronger associations with PD-1, CD40, and ICOS in patients with glioblastoma in both databases." (PMID 31911758, 2020). "Only the triple combination of G47Δ-mIL12, anti-CTLA-4, and anti-PD-1 antibodies successfully cured glioblastoma in an immune-competent glioblastoma mouse model." (PMID 32917034, 2020). "Subsequent analysis showed that CTLA-4 was tightly associated with CXCR3, CXCR6, CXCL12, and T cell immunoreceptor with Ig and ITIM domains (TIGIT) in patients with glioblastoma." (PMID 31911758, 2020). "In preclinical glioblastoma models, systemic CTLA-4 blockade produces an effective T-cell response, tumour shrinkage, and prolongs survival." (PMID 32164579, 2020). "Although several preclinical studies have achieved optimal ORR in glioblastoma mouse models with antibodies targeting PD-1/PD-L1, CTLA-4, TIM-3 LAG-3, IDO, or OX-40, there is still a long time period before these strategies are approved for clinical use." (PMID 30777100, 2019). "From Checkmate 143, we found that nivolumab in combination with CTLA-4 monoclonal antibody (ipilimumab) resulted in 40% of recurrent glioblastoma patients having intolerable treatment-related severe side effects." (PMID 30777100, 2019). "This inhibition can be overcome in vivo by using a CTLA-4 neutralizing antibody, which extended survival in a murine syngeneic glioblastoma model." (PMID 29891009, 2018).
glioblastoma (continued). "The subgroups categorized by cancer types showed significant correlations between CTLA-4 and OS in nasopharyngeal carcinoma, esophageal carcinoma, malignant hematologic diseases, and glioblastoma, most of which had a strong pooled HR." (PMID 28211499, 2017). "Glioblastomas (GBMs) have multiple immunosuppressive effects involving programmed cell death ligand 1 (PD-L1) and CTLA-4 checkpoints." (PMID 28730140, 2017). "In conclusion, a statistically significant relationship was found between the fraction of Treg cells or dynamic expression of CTLA-4 in peripheral blood T cells with survival in glioblastoma patients treated with dendritic cell vaccination." (PMID 22485134, 2012). "We found that decreased Treg cell populations and decreased expression of CTLA-4 on peripheral blood T cells, after DC vaccination, were correlated with longer survival in glioblastoma patients." (PMID 22485134, 2012). "However, targeting the first wave of these molecules, such as PD-1 and CTLA-4, has yielded disappointing overall outcomes in the glioblastoma setting." (PMID 40072074, 2025). "This trial evaluated whether addition of the CTLA-4 immune checkpoint inhibitor ipilimumab to standard therapy improves survival in patients with recently diagnosed glioblastoma." (PMID 40800123, 2025). "In glioblastoma mice with knockout lamp-2a−/− pericytes, the levels of PD-1 and cytotoxic T lymphocyte-associated protein-4 (CTLA-4) were reduced, indicating the lack of toxicity in immune cells." (PMID 38380339, 2024). "Furthermore, a combination of anti-CTLA-4 and anti-PD-1 antibodies have destroyed 75 percent of glioblastomas in mice, compared to 50 percent and 15 percent for anti-PD-1 and anti-CTLA-4 antibodies, as a monotherapy approach." (PMID 36146527, 2022). "It has been reported that the infiltration of macrophages might result in CTLA4-mediated immune suppression and lead to poor prognosis in glioblastoma patients." (PMID 36092735, 2022). "Ipilimumab, a CTLA-4 inhibitor, is used in immunotherapy for glioblastoma multiforme." (PMID 35103180, 2021). "Since the first therapeutic injection of a radioactive compound, nuclear medicine applications have been constantly evolving, and new targets like tumoral microenvironment immune checkpoint inhibitors (e.g., CTLA4 or PD1/PDL1 targets) still need to be explored in the field of glioblastoma treatment." (PMID 31354487, 2019). "However, Checkmate 143 reported that PD-1 checkpoint blockade (nivolumab) in combination with CTLA-4 checkpoint blockade (ipilimumab) resulted in 40% of relapsed glioblastoma patients having intolerable treatment-related severe side effects." (PMID 30777100, 2019). "Moreover, glioblastomas (GBMs) attract CTLA-4-expressing T-cells and express PD-L1, which inhibit activation and continuation of a cytotoxic T-cell response, respectively." (PMID 28730140, 2017). "In both glioblastoma multiforme (GBM) and lower-grade glioma (LGG), ALPK1 showed a significant positive association with four immune checkpoints: PD-L1 (CD274), CTLA-4, LAG-3, and PD-1 (PDCD1)." (PMID 39845963, 2024). "The aim of this clinical trial is to exploit the potential synergy of combined intratumor anti-CTLA-4 mAb (ipilimumab) with systemic PD-1 blockade with nivolumab, while minimizing risks for immune-related toxicity of ipilimumab following resection of recurrent glioblastoma." (PMID 36768997, 2023). "Similarly, Beug and colleagues in an extensive and very detailed study, showed that combining the ICIs, anti-PD1 or anti-Cytotoxic T-Lymphocyte-Associated protein 4 (anti-CTLA-4), with the SM LCL161 greatly increased survival in intra-cranial mouse glioblastoma models and produced durable cures." (PMID 32053868, 2020). "In glioblastoma samples, HVEM expression was shown to coincide with TIM-3, PD-1, PD-L1, CTLA-4, LAG-3, and VISTA." (PMID 40895574, 2025).